GPR35 (G protein-coupled receptor 35)
Diseases named in the same sentence as GPR35 in open-access papers (continued):
Sharing a sentence is not in itself a finding about the gene and the disease.
Stroke (2 papers, 2020 to 2021). Sudden impairment of blood flow to a part of the brain due to occlusion or rupture of an artery to the brain. "Furthermore, neuroprotection mediated by pamoic acid, a potent GPR35 agonist, in stroke associates with an increase in Akt phosphorylation; therefore, ZAP may exert its neuroprotective effect in PD model cells based on DJ-1 deficiency either by inhibiting PDEs or by activating GPR35." (PMID 34697772, 2021). "Since the number of MDMs that express GPR35 were increased after pamoic acid treatment in stroke, we further evaluated the impact of pamoic acid on monocyte infiltration into the ischemic brain in a separate cohort of study." (PMID 32523084, 2020). "Our data reveal that activation of GPR35 by pamoic acid reprograms monocytes that results in improved stroke outcome." (PMID 32523084, 2020). "Treatment with pamoic acid increased the number of GPR35 expressing MDMs in the ischemic brain and improved stroke outcomes." (PMID 32523084, 2020). "Here we show in a mouse model of stroke that GPR35 activation by pamoic acid is neuroprotective." (PMID 32523084, 2020). "So far, the potential of GPR35 to improve CNS disorders especially stroke was unknown." (PMID 32523084, 2020). "Therefore, we investigated the role of GPR35 activation by pamoic acid in a mouse model of stroke." (PMID 32523084, 2020).
ankylosing spondylitis (1 paper, 2025). An autoimmune chronic inflammatory disorder characterized by inflammation in the vertebral joints of the spine and sacroiliac joints. "B3GNT2, GPR35, and PSMG1genes are related to ankylosing spondylitis in the Chinese Han population." (PMID 40736072, 2025).
atrial fibrillation (1 paper, 2026). A disorder characterized by an electrocardiographic finding of a supraventricular arrhythmia characterized by the replacement of consistent P waves by rapid oscillations or fibrillatory waves that vary in size, shape and timing and are accompanied by an irregular ventricular response. "Mechanistically, we demonstrate that epicardial adipose tissues from atrial fibrillation patients secrete kynurenic acid, which acts via GPR35 to disrupt lymphatic endothelial cell metabolism and mitochondrial homeostasis, ultimately promoting endothelial-to-mesenchymal transition." (PMID 42156758, 2026).
cardiac hypertrophy (1 paper, 2015). "The authors also measured GPR35/CXCR8 expression in mouse models of pressure-load induced cardiac hypertrophy; to model, the mice were subjected to transversal aortic constriction (TAC)." (PMID 25926795, 2015).
cardiomyopathy (1 paper, 2022). A disease of the heart muscle or myocardium proper. "Most research was done on doxorubicin-induced cardiomyopathy and for seven genetic variants in CELF4, GPR35, HAS3, RARG, SLC22A17, SLC22A7 and SLC28A3, replication studies were performed without consistent results." (PMID 36536332, 2022).
cervical cancer (1 paper, 2026). A primary or metastatic malignant neoplasm involving the cervix. "GPR35 immunoreactivity was detected in the cytoplasm of cervical cancer cells." (PMID 41496085, 2026). "GPR35 expression was significantly enhanced in cervical cancer tissues." (PMID 41496085, 2026). "Our results indicate that CXCL17/GPR35 axis maybe participate in occurrence and development of cervical cancer." (PMID 41496085, 2026). "As a receptor for CXCL17, we also detected the GPR35 expression pattern in cervical cancer tissues." (PMID 41496085, 2026). "Moreover, we also found GPR35 expression was enhanced in cervical cancer tissues in the present study." (PMID 41496085, 2026). "Therefore, GPR35 expression was significantly enhanced in cervical cancer tissues." (PMID 41496085, 2026). "Moreover, CXCL17/GPR35 axis maybe participate in occurrence and development of cervical cancer." (PMID 41496085, 2026). "In the present study, on the basis of a discovery cohort of 80 cervical cancer specimens, we explored the expression pattern of CXCL17 and GPR35 in cervical cancer cases." (PMID 41496085, 2026).
cholangiocarcinoma (1 paper, 2024). A carcinoma that arises from the intrahepatic biliary tree (intrahepatic cholangiocarcinoma) or from the junction, or adjacent to the junction, of the right and left hepatic ducts (hilar cholangiocarcinoma). "TCGA-CHOL (Cholangiocarcinoma) shows upregulations of HTR3A (35.1-fold) and GPR35 (G Protein-Coupled Receptor 35) (33.9-fold), with downregulations in ADRA1A (−74.3-fold) and ESR1 (Estrogen Receptor 1) (−43.2-fold)." (PMID 39766077, 2024).
conjunctivitis (1 paper, 2018). Inflammation of the conjunctiva of the eye. "It should be noted that lodoxamide, a GPR35 agonist, is an approved drug for conjunctivitis which could potentially be repositioned for IBD." (PMID 30285606, 2018).
COVID-19 (1 paper, 2022). A disease caused by infection with severe acute respiratory syndrome coronavirus 2. "In patients with severe COVID-19, activation of the kynurenine pathway by various cytokines, and tryptophan metabolites regulate immune responses through AhR and GPR35 activation." (PMID 35463998, 2022).
depression (1 paper, 2026). "GPR35 knockdown in the ACC worsens mechanical and thermal hypersensitivity, impairs cognition, increases depression-related behaviors, and amplifies microglial activation and pro-inflammatory cytokine production." (PMID 41913668, 2026).
encephalomyelitis (1 paper, 2023). Inflammation of the brain and the spinal cord. "In addition, encephalomyelitis (EAE) is worsened through the accumulation of GPR35+/Ly6C+ macrophages in the small intestine, while the blockage of KYNA-GPR35 signaling can alleviate EAE." (PMID 38035084, 2023).
endothelial dysfunction (1 paper, 2025). In vascular diseases, endothelial dysfunction is a systemic pathological state of the endothelium (the inner lining of blood vessels) and can be broadly defined as an imbalance between vasodilating and vasoconstricting substances produced by (or acting on) the endothelium. "However, GPR35 has not been extensively linked to endothelial dysfunction, except for a single study demonstrating its involvement in endothelial function and vascular tone modulation." (PMID 39744893, 2025). "Another notable aspect of the current study is the discovery of Thonningianin A and Carfilzomib as potential therapeutic agents for mitigating aging‐related endothelial dysfunction impaired vasodilation by restoring the interaction between TRPV4 and GPR35." (PMID 39744893, 2025). "Subsequently, we revealed that intensive GPR35‐TRPV4 interaction significantly contributes to endothelial dysfunction during aging, utilizing TRPV4 endothelial‐specific knockout (TRPV4EC−/−), AAV‐FLT1‐shRNA (GPR35) mice, and GPR35 overexpressed/knocked‐down HUVECs." (PMID 39744893, 2025).
epilepsy (1 paper, 2026). A brain disorder characterized by episodes of abnormally increased neuronal discharge resulting in transient episodes of sensory or motor neurological dysfunction, or psychic dysfunction. "Our study identifies GPR35 as a druggable target capable of disrupting the vicious cycle of inflammation and hyperexcitability in epilepsy, offering a dual therapeutic strategy to alleviate seizures and cognitive comorbidities." (PMID 41604576, 2026).
Insulin resistance (1 paper, 2022). Increased resistance towards insulin, that is, diminished effectiveness of insulin in reducing blood glucose levels. "It potentially alleviates inflammation and insulin resistance in skeletal muscle and adipose tissues through GPR35/AMPK and SIRT6-mediated pathways." (PMID 35282457, 2022).
intestinal inflammation (1 paper, 2021). "On the one hand, KYNA activates G protein-coupled receptor 35 (GPR35) in the intestinal wall, which may exacerbate chronic stress and DSS-induced intestinal inflammation by affecting nod-like receptor protein 3 (NLRP3)." (PMID 34127024, 2021).
intestine cancer (1 paper, 2022). "Since GPR35 could enhance proliferation and migration in intestine cancer, GPR35 in GC cells were inferred to have the same effect in GC cells based on it has the same transcript expression model in COAD, READ, and STAD." (PMID 36333291, 2022).
lentivirus infection (1 paper, 2023). Virus diseases caused by the Lentivirus genus. "First, the level of GPR35 expression was dose-dependently upregulated by lentivirus infection." (PMID 37113762, 2023).
mastocytosis (1 paper, 2018). A clonal myeloproliferative neoplasm characterized by the proliferation and accumulation of neoplastic mast cells in one or multiple organs or organ systems. "As the evidence listed in the Open Targets platform shows, GPR35 is currently investigated in clinical trials for pruritus and mastocytosis and presents a promising new therapeutic target for a number of disease indications including inflammatory and cardiovascular disease." (PMID 30285606, 2018).
osteosarcoma (1 paper, 2022). A usually aggressive malignant bone-forming mesenchymal neoplasm, predominantly affecting adolescents and young adults. "Furthermore, fluorescence imaging experiments showed ligand-induced internalization of GPR35 in cardiomyocytes and U2OS osteosarcoma cells, but our validated BRET setup did not detect agonist-induced clearance of GPR35." (PMID 35933013, 2022).
pertussis (1 paper, 2024). A contagious bacterial respiratory infection caused by Bordetella pertussis. "This is perhaps surprising as there is substantial literature on the Pertussis toxin-sensitive effects of GPR35 agonists in a range of cells and tissues (see Ref." (PMID 39615676, 2024).
pneumonia (1 paper, 2025). An acute, acute and chronic, or chronic inflammation focally or diffusely affecting the lung parenchyma, caused by an infection in one or both of the lungs (by bacteria, viruses, fungi, or mycoplasma.). "KYNA has been found in some studies that exerts anti-inflammatory effects via the Gpr35 protein in neuroinflammation and pneumonia." (PMID 40862055, 2025).
renal fibrosis (1 paper, 2018). A final common manifestation of a wide variety of chronic kidney diseases characterized by glomerulosclerosis and tubulointerstitial fibrosis. "LV global systolic function, cardiac mass, cardiomyocyte morphology, cardiac fibrosis, renal mass, renal fibrosis, and vascular remodeling in GPR35 knockout mice were found to be comparable to those in wild-type mice." (PMID 29860395, 2018).
stomach adenocarcinoma (1 paper, 2022). "To further explore the role of GPR35 in tumor immunity, we calculated the expression correlation of GPR35 with biomarkers of immune cells in STAD (stomach adenocarcinoma, i.e., GC) using the GEPIA database." (PMID 36333291, 2022).
stomach diseases (1 paper, 2022). "Furthermore, GPR35 in CTSB+ and CD68 + macrophage for EGC had a notable high expression level when compared to those of other stomach diseases." (PMID 36333291, 2022).
temporal lobe epilepsy (1 paper, 2026). A localization-related (focal) form of epilepsy characterized by recurrent seizures that arise from foci within the temporal lobe, most commonly from its mesial aspect. "Single-nucleus RNA sequencing of patients with temporal lobe epilepsy (TLE) and pharmacological models reveals selective GPR35 upregulation in disease-associated microglia." (PMID 41604576, 2026).
tumor (21 papers, 2013 to 2025). "Activation of the GPR35 signaling pathway promotes tumor angiogenesis in the TME, and loss of GPR35 in macrophages reduces matrix metalloproteinase activity in tumor tissues, a prerequisite for tissue remodeling and angiogenesis." (PMID 37005662, 2023). "Deletion of Gpr35 in macrophages profoundly reduces tumour growth in inflammation-associated and spontaneous tumour models caused by mutant tumour suppressor adenomatous polyposis coli." (PMID 33758004, 2022). "The protein level of GPR35 was found to be associated with patients’ age and tumor histological types; patients over 60 years old or whose tumors were adenocarcinoma tended to have high GPR35 expression." (PMID 36614059, 2022). "Altogether, this implied that GPR35 controlled via Na/K-ATPase-dependent Src activation the level of MMP activity in tumours, with the T108M variant yielding highest levels." (PMID 33758004, 2022). "GPR35 on the cell membrane of tumor associated macrophages (TAM) play a vital role in the tumor angiogenesis by activating Na/K ATPase and its downstream signal src kinase to promote the release of angiogenic cytokines such as VEGF and IL-8, which involve in the growth and progression of CAC." (PMID 38273841, 2023). "Moreover, the correlation coefficient values between GPR35 and tumor-associated macrophage markers (VEGF and CD47) were all positive (p < 0.05)." (PMID 36333291, 2022). "GPR35 contributes to tumor cell metabolism by interacting with the α-subunit of the Na+/K+-ATPase, activating Src kinase signaling, and promoting the secretion of the neoangiogenic factors such as VEGF and CXCL1." (PMID 41459506, 2025). "G protein-coupled receptor 35 (GPR35), a member of the largest druggable gene family, has emerged as a critical regulator of tumor metabolism and immune modulation." (PMID 41459506, 2025). "Beyond classical amino acid metabolism, GPR35 regulates osmolyte levels critical for tumor cell survival." (PMID 41459506, 2025). "Together, these findings underscore GPR35’s dual function in shaping inflammatory responses and reprogramming tumor metabolism, making it a promising target for therapeutic intervention in amino acid metabolism-driven cancers." (PMID 41459506, 2025). "In CRC, modulation of GPR35 expression affects fatty acid β-oxidation and phosphatidylethanolamine metabolism, indicating its pivotal role in tumor metabolic regulation." (PMID 41459506, 2025). "In the tumor microenvironment, macrophage GPR35 promotes VEGF, CXCL-1 and MMPs expression through the NKA-Src signaling axis, thereby driving angiogenesis and matrix remodeling." (PMID 41459506, 2025). "On the other hand, GPR35 can also participate in tumor progression through its constitutive activation independent of ligands." (PMID 41459506, 2025). "In this section, we examine the mechanisms by which GPR35 drives tumor development via metabolic reprogramming and highlight potential avenues for therapeutic intervention." (PMID 41459506, 2025). "This would allow for accurately defining the key dependency states driven by GPR35 in tumor progression, providing a theoretical basis and identifying potential therapeutic windows for targeted interventions." (PMID 41459506, 2025). "GPR35 shapes the tumor microenvironment through modulation of metabolite signaling, influencing angiogenesis, immune cell infiltration, and inflammation." (PMID 41459506, 2025). "Within the tumor microenvironment, GPR35 can promote macrophage polarization towards the M2 phenotype and the release of pro-angiogenic factors, thereby indirectly supporting tumor growth and shaping an immunosuppressive microenvironment." (PMID 41459506, 2025). "In PDAC, GPR35 promotes tumor proliferation, metabolic reprogramming and metastasis by activating AKT, stabilizing HIF-1α and regulating autophagy." (PMID 41459506, 2025). "To examine the effect of the NGB-mediated downregulation of GPR35 on tumor angiogenesis, we performed rescue experiments in HCT116 cells." (PMID 37005662, 2023).
tumor (continued). "Recent research reported that activation of the GPR35 pathway drives angiogenesis in the tumor microenvironment." (PMID 37005662, 2023). "The underlying mechanism includes inhibition of CRC metastasis through suppressing tumor angiogenesis, which is achieved by promoting GPR35 protein degradation in the TME." (PMID 37005662, 2023). "Our data showed that the tumor-suppressive function of NGB was mediated by the inhibition of the GPR35/angiogenesis axis." (PMID 37005662, 2023). "Taken together, these results demonstrated that NGB suppresses tumor metastasis by downregulating GPR35 /angiogenesis axis probably." (PMID 37005662, 2023). "Our findings suggested that upregulation of GPR35 expression can possibly assist those aggressive tumor cells to successfully metastasize by promoting anchorage-independent cell growth and even inhibiting anoikis." (PMID 37113762, 2023). "Here, we show that GPR35 on macrophages is a potent amplifier of tumour growth by stimulating neoangiogenesis and tumour tissue remodelling." (PMID 33758004, 2022). "Here, we report that GPR35 on macrophages is a major promoter of tumour growth by facilitating tumour neovascularisation." (PMID 33758004, 2022). "In summary, we identify GPR35 on myeloid cells as upstream coordinator of tumour tissue remodelling, reinforcing the critical role of TAMs and neutrophils in cancer progression." (PMID 33758004, 2022). "Src and ERK1/2 phosphorylation was correspondingly lower in Gpr35–/– compared with Gpr35+/+ tumours." (PMID 33758004, 2022). "Meanwhile, the deletion of GPR35 selectively in the intestinal epithelium was sufficient to reduce tumor numbers." (PMID 36333291, 2022). "Meanwhile, GPR35 were found to have a significant positive relationship with tumor mutational burden (TMB) and tumor purity in GC patients." (PMID 36333291, 2022). "We demonstrate that deletion of Gpr35 in macrophages recapitulates the profoundly reduced tumour size observed in Gpr35–/– germline mutant mice, identifying macrophage GPR35 as a key driver of tumour growth." (PMID 33758004, 2022). "Then, GPR35 was found that there is an obvious significant high expression in GC tumors, when compared to its level in tumor-adjacent (normal) tissues." (PMID 36333291, 2022). "Altogether this demonstrated that pharmacological GPR35 blockade reduced tumour size, involving the Na/K-ATPase—Src pathway delineated herein." (PMID 33758004, 2022). "Activation of the GPR35 pathway promotes tumour growth via two separate routes, by directly augmenting proliferation in epithelial cells that express the receptor, and by coordinating macrophages’ ability to create a tumour-permissive environment." (PMID 33758004, 2022). "It has also been reported that the activation of the GPR35 pathway can directly promote epithelial cell proliferation and coordinate macrophages’ ability to create a tumor-permissive environment." (PMID 36614059, 2022). "It has been reported that GPR35, expressed on macrophages, acts as a major receptor for tumor growth by promoting tumor angiogenesis and MMP activity, mainly due to on Na/K-ATPase-dependent activation." (PMID 34445193, 2021). "Deletion of epithelial GPR35 led to reduced proliferation and tumor burden in this model, showing that in GPR35 contributes to cell turn over in epithelial cells during tumorigenesis." (PMID 34790192, 2021). "Other receptors, such as GPR18 and GPR35, have also been identified as modulators of tumor progression, but the actual effect of cannabinoids on these receptors is still unclear." (PMID 31611800, 2019). "Expression difference of GPR35 between normal and tumor tissues." (PMID 41459506, 2025). "In recent years, the role of GPR35 in tumor development has gained increasing attention." (PMID 41459506, 2025).